CD4 (CD4 molecule)
Diseases named in the same sentence as CD4 in open-access papers (continued):
Sharing a sentence is not in itself a finding about the gene and the disease.
influenza (continued). "Transfer of influenza-specific effector CD4+ T cells into T cell-deficient mice accelerates production of neutralizing Abs, thus cross-reactive memory CD4+ T cells can potentially enhance B cell responses during infection with a novel influenza virus." (PMID 24971078, 2014). "It was recently reported that antibodies against surface molecules of influenza virus fail to neutralize variant influenza strains, but CD4+ T cells that recognize internal conserved influenza proteins limit virus shedding and disease severity." (PMID 25232948, 2014). "Reduced IL-2 production by CD4+ T-cells has been associated with decreased antibody responses to influenza vaccination in older people." (PMID 24842313, 2014). "In mice, repeated stimulation of CD4 T cells reduced the percentage of cells secreting effector cytokines in vitro, and this was associated with reduced protection from influenza challenge." (PMID 23526940, 2013). "Future studies should investigate the association between reduced naturally-acquired influenza-specific CD4+ T-cell immunity and naturally-acquired influenza-specific antibody responses in HIV-infected individuals." (PMID 22715399, 2012). "ICOS−/− mice developed significantly fewer influenza-specific EM CD4 T cells and were more susceptible to re-infection than wild-type mice." (PMID 21364749, 2011). "Pie chart analyses summarize the differential distribution of influenza-specific CD4 cells and underline the impact of vaccination route on the quality of vaccine-specific effector T cells." (PMID 20520820, 2010). "Baseline percentage of fluA-specific CD4 was associated with fold-change in percentage of flu-specific CD4 T-cells (p = 0.0003)." (PMID 18596908, 2008). "Smoke exposure before influenza was associated with fewer CD4+ and CD8+ lymphocytes in LNs at both d3 and d10, and a large increase in both types of lymphocytes in BALF at d10." (PMID 18627612, 2008). "Protection against influenza infection has been associated with various factors, including the presence of influenza-specific serum antibodies, polyfunctional B and T cells, particularly IFNγ-producing CD4+ T cells, memory CD8+ T cells, and CD38+ plasmacytoid dendritic cells (pDCs)." (PMID 40766325, 2025). "Severe and life-threatening influenza is characterized by lymphopenia, with a decrease in circulating CD4+ and CD8+ T cells, γδ T cells, and mucosal-associated invariant T (MAIT) cells, along with an excessive release of proinflammatory cytokines and chemokines (cytokine storm)." (PMID 40766325, 2025). "Consequently, Aiolos-deficient CD4+ T cells exhibit increased production of cytotoxic effector molecules, including perforin and granzyme B, during responses to influenza infection." (PMID 36964178, 2023). "Moreover, it has been demonstrated that memory CD4+ T cells recognizing immunodominant epitopes of the M1 and NP proteins were associated with the reduction in influenza symptoms and the limitation of viral replication in experimentally infected humans." (PMID 36986773, 2023). "In addition, we showed that immune stability was associated with immune immunotypes and circulating CD38+ CD4+ T follicular cell increase 7 days after influenza vaccination." (PMID 36081314, 2022). "Furthermore, we show that longitudinal intra‐individual variation, which reflects immune stability, was associated with circulating CD38+ CD4+ T follicular cell kinetics 7 days after influenza vaccination." (PMID 36081314, 2022). "The study showed that coinfection with aspergillosis increased all-cause mortality in severe influenza from one-quarter to one-half of cases, along with higher white blood cell, neutrophil granulocyte, procalcitonin, and lower CD4 + T-cell counts in the death group." (PMID 35628717, 2022). "Additionally, In HIV-infected postmenopausal women, we reported a TNF-α–mediated impairment of CD4 and pTfh function associated with poor antibody responses to influenza vaccination." (PMID 34491910, 2021).
influenza (continued). "Next, we investigated whether CD4+ T cells or monocytes were associated with changes in autosomal-iSEXS scores during influenza infection." (PMID 31722210, 2019). "Interestingly, the limited CD4 T-cell repertoire diversity in aged individuals, probably a consequence of reduced thymic function, has been associated with a poor response to influenza vaccination in a mouse model." (PMID 31312227, 2019). "Consequently, the ability of the immunizing antigen to elicit CD4+ T cell help in the context of diverse MHC class II alleles should be an important consideration in the design of stem-based universal influenza vaccines." (PMID 30521496, 2019). "Consequently, baicalin impacted the differentiation tendency of CD4+ T cells and run a mild type 1 inflammatory response to anti-influenza, which controlled inflammatory damage caused by IAV infection." (PMID 29681974, 2018). "Among HIV-infected participants, individuals with enrollment CD4+ cell counts <200/μL had a higher incidence of influenza-associated ILI than those with counts >200/μL, but the association was nonsignificant (79.1 vs 40.5 per 1000 PY; IRR, 1.95; 95% CI.78–4.92)." (PMID 29045699, 2018). "However, in recent years a subset of CD4+ T cells, known as T follicular helper (Tfh) cells have been strongly implicated to be involved in robust, long-lived antibody responses to influenza infection and immunization with TIV and ATIV." (PMID 29326687, 2017). "However, humans have a complex immunological history with influenza through periodic infection and vaccination with seasonal variants, leading to the establishment of heterogeneous memory populations of CD4 T cells that participate in subsequent responses." (PMID 26834750, 2016). "Two reviews of the published data on influenza epidemiology in HIV-infected individuals found that HIV-infected individuals experience higher rates of influenza-associated mortality as compared to HIV-uninfected individuals especially at low CD4+ T cell counts." (PMID 25786103, 2015). "While memory CD4 T cells specific for conserved determinants have been implicated in protection in animal models and young humans, dissecting the precise role of this arm of influenza immunity in aged humans is an important goal for future studies." (PMID 24155927, 2013). "Our study, therefore provides some evidence to suggest that the impaired influenza-specific CD4+ T-cell immunity may be responsible in part for the increased risk in influenza-associated complications in HIV-infected persons." (PMID 22715399, 2012). "Furthermore, the defect in effector memory CD4 T cells after infection with influenza was associated with significantly more weight-loss after challenge with a heterosubtypic influenza strain." (PMID 21364749, 2011). "Thus, it is possible that the lower efficacy of our inactive influenza viral vaccine in the IL-6 deficient mice could be due to impaired memory CD4/CD8 T cell response and the subsequent antibody response." (PMID 33193346, 2020). "Also important to consider is that because of error prone polymerase in influenza virus, T cell epitopes in influenza proteins can accrue small mutations, leading to emergence of variants that may stimulate only a subset of the memory CD4 T cells." (PMID 31134060, 2019). "While flu-related deaths can be caused by many factors, age-related declines in immune function contribute significantly and lead to multiple age-related manifestations such as delayed and reduced signaling and cytokine secretion by CD4+ T cells in response to flu antigens." (PMID 29616390, 2018). "One study did report higher frequencies of peripheral and respiratory virus-specific CD4+ T-cells post-infection in severe influenza, although, whether T-cells caused severe disease or if this was a result of uncontrolled viral replication is difficult to distinguish." (PMID 27242800, 2016).
influenza (continued). "The authors demonstrated that previous seasonal influenza infections have seeded a broad pool of cross-reactive memory T cells, with ~70% of catalogued CD4+ and 60% of CD8+ epitopes being ≥90% conserved in circulating clade 2.3.4.4b viruses." (PMID 41350922, 2026). "Nonetheless, influenza vaccination was able to trigger peripheral blood T-cell activation, with CD4+ lymphocytes producing the Th1 cytokine IFN-γ, both in patients vaccinated more than 6 months post-transplant and in those immunized earlier." (PMID 41522680, 2026). "Thus, preexisting IgG antibodies, age, and CD4 TE+EM cells could serve as predictors for the successful influenza vaccination in this at-risk population informing targeted interventions to improve vaccine responses, prevent infections, and reduce influenza-associated comorbidities." (PMID 41812549, 2026). "Our findings are well in line with previous studies showing that inactivated influenza vaccines (IIV) primarily induce CD4+ T-cell responses." (PMID 41350922, 2026). "Synergistically engaging ASCs, cTfh, MBCs, and CD4+ T cells to enhance immunological memory and establish long-term vaccine-induced immunity should be considered in future influenza vaccine design." (PMID 41166714, 2026). "In the context of infection, an early study examined how TCF1+ CD4+ T cells function as Th1 progenitors during influenza infection." (PMID 40634636, 2025). "As antigenic stimulation we chose the model antigen influenza vaccine since it can activate high percentages of antigen-specific CD4+ T cells due to high prevalence of influenza infection or vaccination." (PMID 40706797, 2025). "We therefore studied the role of BLIMP1 in regulating IL-2 signaling in CD4+ T cells from influenza-infected mice." (PMID 40680114, 2025). "IMU-935 prominently reduced the response of antigen-specific CD4+ T cells to influenza antigens, as evidenced by a reduced proliferation." (PMID 40706797, 2025). "Memory CD4+ T cells play a crucial role in long-term immunity against influenza by supporting both localized and systemic responses upon re-exposure." (PMID 40872830, 2025). "CD4+ T cells are key participants in the formation of both humoral and cellular immune responses during influenza vaccination, contributing to the protection against infection." (PMID 41295490, 2025). "Nevertheless, CD4+ T cells in cattle are expected to exhibit conserved antiviral functions across different influenza infections, while also showing virus-specific adaptations in epitope recognition, cross-reactivity, and regulatory mechanisms." (PMID 40872830, 2025). "IL-2 signaling has been shown to be highest at the peak of influenza infection in various CD4+ T cell populations, such as TFH, TFR, TEFF, and Treg cells." (PMID 40680114, 2025). "This phenomenon has also been observed with other vaccines, in which HIV-infected individuals with CD4+ T cell counts ≤ 350 were less likely to achieve seroconversion after inoculation with the influenza vaccine." (PMID 40266154, 2025). "Lung-resident dendritic cells, activated by epithelial cell-derived chemokines (e.g., CCL2, type I/III interferons), induce the development of influenza-specific CD4+ and CD8+ T cells." (PMID 40331962, 2025). "Early CD4+ Tfh coordination in draining lymphoid tissue underpins robust responses to adjuvanted influenza vaccine that transcend ancestral inter-individual variation in young adults, with implications for vaccine design in ancestrally-diverse populations." (PMID 41317665, 2025). "Our data and others suggest the pool of cross‐reactive CD4+ T cells established by seasonal influenza exposure is limited, and that pre‐priming is required to support the immunogenicity of H5 vaccines." (PMID 41395356, 2025). "Overall, these results are consistent with BLIMP1 controlling influenza infection, at least in part, by regulating IL-2 signaling in CD4+ T cells." (PMID 40680114, 2025).
influenza (continued). "Our results join other recent studies that have identified functionally heterogeneous populations of lung-resident CD4+ T cells following influenza infection." (PMID 41256356, 2025). "During influenza infection in mice, induction of Arg1 expression is a key feature of lung CD4+ T cells." (PMID 39858200, 2025). "The mouse model of influenza infection recapitulates the dynamics of virus morbidity and the immune response seen in human infection, and results in the generation of lung CD4 and CD8 tissue resident memory T cells (TRM)." (PMID 40060443, 2025). "The identified biomarker panel (CD4/CD8 ratio, IL-6, Kyn/Trp ratio) shows potential clinical promise for early risk stratification in high-risk pregnancies with influenza infection." (PMID 40558593, 2025). "CD4+ T cells mount antiviral responses against influenza by facilitating humoral immunity, supporting CD8+ T cell priming and mediating immune regulation." (PMID 40872830, 2025). "B cell responses to influenza are predominantly CD4+ T cell-dependent, with T follicular helper cells playing a central role in driving high-affinity antibody production." (PMID 40872830, 2025). "An example is seen during influenza infection, where heterogeneous lung‐resident CD4 T cell subsets, including TRH and Th1 cells, are found in and around iBALT." (PMID 40815083, 2025). "Vaccination with seasonal inactivated influenza vaccine drives a modest, transient expansion of B cells and CD4+ T cells recognising avian influenza strains." (PMID 41395356, 2025). "Severe influenza and COVID-19 patients exhibit delayed and diminished virus-specific CD4+ and CD8+ T cell responses compared to mild cases." (PMID 39883362, 2025). "Although immunogenicity was thoroughly assessed via HI and MN assays, earlier data from a phase 1a trial in younger adults also demonstrated the ability of LVA to induce influenza-specific CD4+ T-cell responses." (PMID 41012125, 2025). "For instance, single-cell analyses revealed that CD4+ TRM cells in nasal tissue not only persist long after influenza infection, but are also key to heterosubtypic protection and tissue preservation, with their residency governed by the CXCL16–CXCR6 axis." (PMID 40407543, 2025). "In contrast, in the influenza infection model, antigen-specific CD4+ T cells bifurcate into TCF1+ and TCF1– populations only after four to five divisions." (PMID 40634636, 2025). "The Davis group previously documented the presence of CD4+ T cells specific to viral antigens in unexposed humans and demonstrated that immunization with influenza vaccine generates influenza-specific memory T cells with cross-reactivity to unrelated microbes." (PMID 40279312, 2025). "In part 1, preexisting influenza strain-specific CD4+ T-cell responses were observed at baseline across the mRNA-1010 (50, 100, and 200 μg) and placebo groups, indicating previous influenza exposure." (PMID 38934845, 2025). "Influenza infection studies conducted in healthy patients demonstrated that preexisting memory CD4+ T cells responded to influenza proteins of the challenge virus strain and correlated with decreased disease severity." (PMID 40279312, 2025). "The percentage of SCoV-2-specific CD4+ T-cells in the lymphocytes was higher than the percentage of influenza-specific CD4+ T-cells." (PMID 40266139, 2025). "In a human influenza challenge study, a higher baseline frequency of cytotoxic CD4+ T cells correlated with decreased viral shedding, lower symptom scores, and reduced disease duration after exposure." (PMID 41235706, 2025). "Matrix-MTM, for example, has shown promising results in enhancing antibody responses and CD4+ T cell immunity in the context of NanoFlu—a novel adjuvanted recombinant influenza vaccine currently in late-stage clinical trials." (PMID 41295535, 2025).
influenza (continued). "In contrast to their presumed pathologic roles in autoimmunity, cytotoxic CD4+ T cells can be protective and have been shown in mice to provide direct defense against lethal influenza infection." (PMID 41235706, 2025). "mRNA-1010 demonstrated durable humoral responses, higher influenza A HAI GMTs and broader antibody responses than a licensed quadrivalent influenza vaccine (Afluria), and robust cellular CD4+ T-cell responses as compared with placebo." (PMID 38934845, 2025). "T cell–mediated immunity against influenza infection depends on CD4+ T cells to provide help shape CD8+ T cell metabolism." (PMID 40857407, 2025). "In mice, lung-derived CCR9+CD4+ T cells migrate to the small intestine via the CCL25/CCR9 axis during influenza infection, contributing to dysbiosis and IL-15-driven Th17 polarization that exacerbates IL-17A-mediated intestinal injury." (PMID 40872830, 2025). "Wherry and colleagues also showed expansion of circulating CD4+ Tfh cells in anti–PD-1–treated patients after influenza vaccination correlated with the development of IrAEs (P = 0.06)." (PMID 40626363, 2025). "In PLWH, where pneumonia is mostly polymicrobial, the rapid decrease in the number of CD4 T lymphocytes in the presence of concomitant influenza infection facilitates the emergence of PCP." (PMID 40260188, 2025). "We show that DCCs impair lung T cell activation and that CD4+ T cells sustain the pulmonary metastatic burden after the influenza infection by inhibiting CD8+ T cell activation and cytotoxicity." (PMID 40739350, 2025). "The HA peptide binds to multiple HLA-DR molecules and participates in the influenza-specific CD4 T-cell response in multiple donors to its HLA-DR promiscuity." (PMID 41383601, 2025). "Critical work from Susan Swain and her group using mouse models of influenza established a role for memory CD4+ T cells in protection against heterosubtypic strains of virus." (PMID 40279312, 2025). "Pre-clinical evaluation of virus-vectored candidate vaccines indicate that the presence of CTL91 and CD4+92 T-cells recognizing highly conserved influenza proteins generates heterosubtypic immunity across IAV strains." (PMID 39805898, 2025). "Memory CD4+ T cells, generated following primary infection, provide long-lasting immunity by quickly responding to re-exposure to influenza, ensuring rapid and robust immune protection." (PMID 40872830, 2025). "For instance, CD4+ T cells recognizing highly conserved influenza proteins can generate cross-protective immunity across different IAV subtypes in cattle." (PMID 40872830, 2025). "In an influenza model of infection, inducible deletion of Bcl6 in CD4 T cells, after iBALT formation, led to an emigration of CD4 T cells away from B‐cell clusters." (PMID 40815083, 2025). "Children, compared to adults, exhibit a delayed but intact influenza-specific CD4+ T cell response, leading to suboptimal activation of CD8+ cytotoxic T lymphocytes (CTLs) and prolonged inflammation." (PMID 39883362, 2025). "CD4+T cells are necessary for the formation of protective CD8+ TRM cells during influenza infection; IFN-γ is an essential signal for this process." (PMID 40698364, 2025). "Tregs limit CD8+ T cell and NK cell proliferation via IL-10 and TGF-β production while promoting Tfh cell differentiation in CD4+ T cells by sequestering IL-2, thereby enhancing germinal center B cell responses in influenza infections." (PMID 40872830, 2025). "This study utilised fine needle biopsy to isolate key CD4+ T‐cell subsets from human lymph nodes following seasonal influenza vaccination to assess the potential for adaptability and flexibility in these lymph node cell populations." (PMID 41143063, 2025). "Memory CD4 T cells, in particular, have been shown to significantly impact heterosubtypic immunity against various influenza strains, enhancing both the speed and efficacy of viral clearance." (PMID 39898643, 2025).